CTLA4 (cytotoxic T-lymphocyte associated protein 4)
Diseases named in the same sentence as CTLA4 in open-access papers (continued):
Sharing a sentence is not in itself a finding about the gene and the disease.
cancer (continued). "The immune checkpoint inhibitor ipilimumab inhibits cytotoxic T-lymphocyte associated protein 4 (CTLA4 or CD152) and renders exposed cancer cells sensitive to T-cell mediated destruction." (PMID 32363000, 2020). "Novel cancer immunotherapies such as anti-cytotoxic T-lymphocyte-associated protein-4 (CTLA-4) and anti-programmed death-1/programmed death-ligand-1 (PD-1/PD-L1) monoclonal antibodies have revolutionised cancer therapy." (PMID 33081170, 2020). "The immune checkpoint receptor CTLA-4 plays a crucial role in the negative regulation of T-cell activation of cancer cells to evade immune response and maintain self-tolerance." (PMID 31960110, 2020). "CTLA4 blockage increased effector memory T cells in our study, which is similar to the observations in cancer patients who receive the CTLA4 inhibitor ipilimumab." (PMID 32872393, 2020). "Extensive studies show significant improvement in cancer immunotherapy with antibodies targeting CTLA-4 (approved antibody ipilimumab) and PD-1/PD-L1 in various cancer types." (PMID 32731620, 2020). "This includes Programmed death-ligand 1 (PDL1), Programmed cell death protein 1 (PD1), cytotoxic T-lymphocyte-associated protein 4 (CTLA4), CD20 and CD54 for different cancers." (PMID 32576886, 2020). "The other major group of immune checkpoint inhibitors that have become increasingly utilized in cancer are the CTLA-4 inhibitors of which ipilimumab is the classic example." (PMID 32075140, 2020). "Lines B04 and B64 manifested increased resistance to combined anti-PD-1/anti-CTLA-4, demonstrating that the cancer clones enriched in the ICB responders were more resistant to ICB treatment." (PMID 33059736, 2020). "Currently, the most prevalent immune checkpoint receptors that have been used to manipulate the immune system for cancer immunotherapy are PD1 and cytotoxic T-lymphocyte-associated protein 4 (CTLA-4); both are T-cell surface receptors." (PMID 32316469, 2020). "The comprehensive ranking of major cancer types provides a roadmap for clinical development of the next generation of anti-CTLA-4 antibodies." (PMID 31991588, 2020). "Notwithstanding these achievements, the therapies targeting immune checkpoints CTLA4 and PD-1 pathways signify a revolution in cancer treatment." (PMID 33297561, 2020). "In conclusion, the results of our pan-cancer analysis indicate that PD-1 and CTLA4 are useful prognostic biomarkers in some cancer types." (PMID 33072070, 2020). "A growing number of experiments have illustrated that the synergy of RT and CTLA-4 inhibitors effectively improves the survival of cancer patients." (PMID 32992835, 2020). "As in mice, longitudinal immune monitoring in patients with MM, provided evidence that high butyrate was associated with less accumulation of memory and less ICOS induction on T cells in hosts with cancer and treated with anti-CTLA-4." (PMID 32358520, 2020). "By blocking the checkpoints PD-1/PD-L1 and CTLA4/B7, the cellular mediated anti-tumor activity of the immune system is then successfully restored and the cancer cells can be efficiently eliminated by the immune system." (PMID 32785162, 2020). "Two monoclonal anti-CTLA-4 antibodies, Ipilimumab and Tremelimumab, are currently used in cancer to release the brake induced by CTLA-4 and build an effective immune response." (PMID 32793228, 2020). "Cancer patients undergoing treatment with anti-PD-1/PD-L1 or anti-CTLA-4 immune checkpoint inhibitors (ICI) currently, constitute a growing population." (PMID 32549075, 2020). "Targeted blockade of CTLA-4 and PD-1/PD-L1 as forerunner molecular targets of cancer-related immune exhaustion has rapidly extended to HCC based on the promising results of ICPI therapy in multiple indications." (PMID 32157213, 2020). "Further studies have found that the anti-cancer effect of CTLA-4 blockers depends on different Bacteroides species." (PMID 32522267, 2020).
cancer (continued). "Currently, the main treatment method of patients with cancer is blocking CTLA-4 and PD-1 pathways and CAR T cell therapy." (PMID 32164594, 2020). "The use of anti-CTLA-4 immunotherapy in other types of cancer has been hampered by the limited understanding of driving responses and resistance pathways." (PMID 32850353, 2020). "Currently, inhibitors of cytotoxic T-lymphocyte-associated protein 4 (CTLA-4), programmed cell death protein 1 (PD-1) and its ligand (PD-L1) are well known and have been approved for several cancer treatments." (PMID 33374927, 2020). "Antibodies targeting the immune-checkpoint proteins CTLA-4, PD-1, and PD-L have become new therapies for cancer." (PMID 32486493, 2020). "Unfortunately, cancer and immune cells express checkpoint ligands such as programmed death-ligand 1 (PD-L1) and CTL-associated antigen 4 (CTLA-4), which bind to CD8+ T cells and repress their T-cell receptor (TCR) signaling, proliferation, and motility." (PMID 32752017, 2020). "This cohort included 1,661 patients with metastatic or unresectable cancers treated with antibodies targeting CTLA-4, PD-1/PD-L1, or both." (PMID 32676589, 2020). "Since the FDA approval of ipilimumab (human IgG1 k anti-CTLA-4 monoclonal antibody) in 2011, six more immune checkpoint inhibitors (ICIs) have been approved for cancer therapy." (PMID 32245016, 2020). "Nowadays, immune checkpoint inhibitors (ICI) which include anti-CTLA4, anti-PD-1 and anti-PD-L1 antibodies are in clinical use for the treatment of numerous cancers." (PMID 32244396, 2020). "Among the immune checkpoint inhibitors, PD-1/PD-L1 and CTLA-4 inhibitors showed promising therapeutic outcomes, and some have been approved for certain cancer treatments (e.g., melanoma), while others are under phase III and IV clinical trials." (PMID 33282963, 2020). "Reportedly, the systemic administration of a checkpoint antibody (anti-CTLA4) inhibited the immune suppressive molecules that heavily influence the immune response against cancer cells." (PMID 33505987, 2020). "Cancer immunotherapies, particularly ICBs targeting the PD-1/PD-L1 and CTLA-4 immune checkpoints, have made great success in a variety of malignancies over the past decade and have revolutionized treatment strategies for many cancer patients." (PMID 33223512, 2020). "Based on initial studies on mouse tumors, anti-CTLA-4 antibodies were tested in clinical trials for human cancers." (PMID 31974523, 2020). "Immune checkpoint inhibitors (ICI) targeting the PD-1 or CTLA-4 pathways have revolutionized cancer therapy in the last decade." (PMID 33154756, 2020). "Based on median transcript levels, there are about 20-fold differences between the highest and lowest CTLA4-expressing cancer types." (PMID 31991588, 2020). "Immunotherapies targeting CTLA-4 and PD-1 have elicited promising responses in a variety of cancers." (PMID 33250890, 2020). "This is because CTLA-4 is negatively regulating virtually all immune reactions, while PD-1 is suppressing only a limited type of immune responses, like those against cancer cells." (PMID 32492969, 2020). "A study found that the expression of immune checkpoints such as PD-1/PD-L1 and CTLA-4 plays a pivotal role in the balance and escape phase of cancer immunity." (PMID 32522267, 2020). "In the past decade, the development of immune checkpoint inhibitors (ICPIs) such as PD-1/PD-L1 and CTLA-4 inhibitors provided a breakthrough in the cancer therapies as evident by the increasing FDA approvals in recent years." (PMID 32340193, 2020). "PD-1 inhibitors along with anti-CTLA-4 antibodies have received FDA approvals for a range of cancers and trials involving other inhibitory checkpoints, such as LAG-3 and TIM-3 are ongoing." (PMID 33250900, 2020). "Checkpoint inhibitors (CPIs) reactivate T lymphocytes to recognize cancer cells by blocking CTLA-4 or PD-1, and are therefore effective in numerous types of cancer, but have several immune-related adverse effects." (PMID 33261023, 2020).
cancer (continued). "Immune checkpoint inhibitors like anti-PD1/PDL1 and anti-CTLA4 help to regulate the expression of immune checkpoint molecules that can be used by cancer cells to evade attacks by the immune system." (PMID 33178201, 2020). "This review will summarize current knowledge about the impact of the genetic variants of CTLA-4, PDCD1, PD-L1, BTLA, TIM-3, and LAG-3 on cancer risk." (PMID 33519815, 2020). "Targeting inhibitory receptors/checkpoint molecules like CTLA-4 and PD-1 has promising effects in cancer therapy." (PMID 33519807, 2020). "The CTLA-4 and PD-1, two common immune checkpoint inhibitors (ICIs) on activated T cells, are the most reliable targets for cancer treatment." (PMID 32620130, 2020). "Cytotoxic T-lymphocyte-associated antigen 4 (CTLA-4) and programmed cell death protein-1 (PD-1) are the two most well studied immune regulatory checkpoint pathways in cancer." (PMID 31748961, 2020). "Antibodies against CTLA-4, PD-1, and PD-L1 have demonstrated durable clinical responses and have been approved by the U.S. Food and Drug Administration for various cancers." (PMID 32775303, 2020). "Recently, cancer immunotherapy, including blockade of inhibitory immune checkpoints (such as PD-1/PD-L1 and CTLA-4), has emerged as an unprecedented breakthrough for the treatment of cancer that can induce long-term tumor regression (10, –12)." (PMID 31888983, 2020). "Currently, the immune checkpoints (PD-1, CTLA-4) inhibition represents a valid strategy for treatment of different types of cancers." (PMID 32982967, 2020). "ICB-based therapies targeting CTLA-4 or PD-1 have shown a promising future in multiple cancer types, but the molecular mechanism between them is completely different." (PMID 32154170, 2020). "Immune checkpoint blockade using therapeutic antibodies against CTLA-4 and PD-1 for cancer immunotherapy results in autoimmune clinical syndromes in a proportion of individuals." (PMID 32075963, 2020). "The first monoclonal antibodies that were tested clinically in human cancers targeted CTLA-4 and PD-1 and have now become common therapies in several cancers." (PMID 32316916, 2020). "The purpose of this study was to investigate the in vivo therapeutic efficacy of the combination of CD44-targeted NIR-PIT and CTLA4 blockade in several syngeneic mouse models of cancer." (PMID 32937841, 2020). "Although substantial clinical responses have been achieved in cancer patients treated with antibodies against the CTLA-4 and PD-1/PD-L1 checkpoints, only a small portion of patients have responded to such therapies in several cancers." (PMID 33425759, 2020). "Two of these co-inhibitory ICs, CTLA-4 and PD-1, have been studied extensively for their roles in cancer." (PMID 32290124, 2020). "Our approach provides an objective ranking of the sensitivity of human cancers to anti-CTLA-4 antibodies." (PMID 31991588, 2020). "Inhibitors of CTLA-4 have also been shown to have remarkable success in clinical cancer immunotherapy in recent years." (PMID 31911758, 2020). "Since the success of CTLA-4 and PD-1 immune checkpoint inhibitors, increasing attention has been paid to cancer immunotherapy." (PMID 32793196, 2020). "The basic principle of immune checkpoint inhibitors (ICIs) is to block the CTLA-4 and the PD-1/PD-L1 pathways in order to enhance T-cell action against the cancer cells." (PMID 32294888, 2020). "Recently, the effects of immune checkpoint inhibitors (ICIs), including anti-CTLA-4 antibodies and anti-PD-1/PD-L1 antibodies, on various malignant tumors have been reported." (PMID 32326079, 2020). "This new generation of anti-CTLA-4 antibodies will likely lead to a new wave of clinical studies testing CTLA-4 targeting for cancer immunotherapy." (PMID 31991588, 2020). "As such, serum CTLA-4 levels in the cancer group were significantly higher than those in the healthy group (P = 0.022)." (PMID 32123292, 2020).
cancer (continued). "Depending on immune contexture, immune checkpoint inhibitors (ICIs), such as anti-PD1/PD-L1 and anti-CTLA-4, elicit potent antitumor effects and have been approved in various cancers types." (PMID 32526888, 2020). "Anti-CTLA-4 therapy is thought to prime T cells, whereas anti-PD-1 therapy is involved later in activation of immune effector response at the cancer cell level." (PMID 32630247, 2020). "This is the largest multicenter study to date examining the risk of GI adverse events in patients with cancer and underlying IBD who received immunotherapy with CTLA-4 or PD-1/PD-L1 inhibitors." (PMID 31800340, 2020). "As PD-1 is the major regulator of T cell exhaustion, together with other inhibitory receptors like CTLA-4 or TIM-3, T cells with high PD-1 expression lose the ability to eliminate cancer, and PD-1+ TILs are therefore associated with poor clinical outcome." (PMID 32708639, 2020). "Based on this consideration, many current immunotherapeutic agents like CTLA-4 and PD-L1 inhibitors target steps in the cancer immunity cycle." (PMID 33392186, 2020). "CTLA-4, PD-1, or PD-L1 have shown strong antitumor activity in the experimental animal models and the long-lasting clinical efficacy in cancer patients, such as melanoma, renal cell cancer, and lung cancer." (PMID 33488618, 2020). "Ipilimumab and Nivolumab, targeting the molecules CTLA-4, PD-1, respectively,have shown efficacy against several types of cancer." (PMID 33239030, 2020). "After blocking the functions of CTLA-4 or PD-1 by using antibodies, the same patterns of things happen in cancer patients: serious and grave side effects with the CTLA-4 antibody; and only mild adverse events with the PD-1 antibody." (PMID 32492969, 2020). "The blockade of PD-1 and CTLA-4 with mAbs in cancer patients often leads to severe irAEs in multiple tissues, including the skin, intestine, liver and lung." (PMID 31974523, 2020). "IrAEs have a high incidence in multiple types of cancers, with anti-CTLA-4 therapy, ipilimumab, and anti–PD-1 or anti–PD-L1 therapies, at 90 and 70%, respectively." (PMID 33123161, 2020). "The recognition of the important role of CTLA-4 led to the development of inhibitory antibodies blocking its function, as an attractive strategy for cancer treatment." (PMID 32024070, 2020). "The discovery that CTLA-4 inhibits T cell activation made it an attractive target for cancer immunotherapy, leading to the development of inhibitory antibodies blocking its function." (PMID 32781690, 2020). "Anti-PD-1/PD-L1 and anti-CTLA-4 mAb combination strategies have been evaluated in various types of cancers." (PMID 32218257, 2020). "In recent years, immune checkpoint inhibitors (ICIs) have opened a new era of immunotherapy in vary cancers, represented by anti-CTLA-4 and anti-PD." (PMID 33613554, 2020). "Anti-CTLA-4 and anti-PD-1 antibodies both target inhibitory molecules on T cells and are used to treat similar types of cancer." (PMID 32944086, 2020). "Monoclonal antibodies targeting programmed death-1 (PD-1) and cytotoxic T-lymphocyte antigen 4 (CTLA4) are widely known drugs and have proven strikingly powerful in augmenting anti-cancer immunity led to the elimination of cancer cells." (PMID 32636970, 2020). "PD-1 and CTLA-4 have so far received the most attention and as such their roles in cancer immunology are now well characterized." (PMID 32316916, 2020). "We performed GSEA to assess the biological significance of PD-1 and CTLA4 expression in different cancers." (PMID 33072070, 2020). "Immune checkpoint receptors, such as TIGIT, PD-1 and CTLA-4, have been discovered to be highly expressed in numerous types of cancer, and they are currently being targeted to improve antitumor and T or NK cell responses." (PMID 32903786, 2020). "Blockade of PD-1/PD-L1 and/or CTLA-4 has been demonstrated to be effective and durable in certain types of cancers." (PMID 33256070, 2020).
cancer (continued). "In 2000, two CTLA-4–blocking MoAbs, ipilimumab and tremelimumab, entered clinical trials for treatment of patients with cancer." (PMID 32018226, 2020). "Authors also reported a negative correlation between CTLA-4 expression and miR424-3p expression in PC tissues, highlighting the role of miR424-3p in regulating CTLA-4 expression in PC as it has been reported in other cancer types." (PMID 32760400, 2020). "PD-L1 (CD274) and CTLA4 are two well-studied immune checkpoints targeted for the treatment of patients with cancer." (PMID 33479597, 2020). "(namely B. fragilis) and Burkolderiaceae family members, involved in the IL-12-dependent priming of Th1 cells as well as the immunostimulatory and anti-cancer effects of CTLA-4 blockade." (PMID 33381121, 2020). "Antitumor T-cell responses are critical to impeding cancer progression and can be targeted for therapy: clinical trials that block inhibitory receptors (IRs), such as PD-1 and CTLA-4, have shown great success." (PMID 32451453, 2020). "In recent years, the immune checkpoint proteins such as cytotoxic T-lymphocyte antigen 4 (CTLA-4) or the programmed cell death ligand 1/protein 1 pathway (PD-L1/PD-1) have been used as crucial targets for immunotherapy in many cancers, including LUAD." (PMID 32143735, 2020). "Anti-PD-1/PD-L1 and anti-CTLA-4-based immune checkpoint blockade (ICB) immunotherapy have recently emerged as a breakthrough in human cancer treatment." (PMID 33203146, 2020). "The remarkable success of these mAbs have been highlighted by the FDA approval of α-PD-1, α-PD-L1, and α-CTLA-4 mAbs for a number of cancers, and more recently by the Nobel Prize in physiology and medicine to Tasuku Honjo and James Allison." (PMID 32435621, 2020). "Immunotherapy, predominantly immune-check point inhibitors (ICIs) enhance immune-mediated anticancer activity by blocking immune-attenuating interactions of CTLA-4/B7 or PD-1/PD-L1 receptors between T-lymphocytes and cancer cells." (PMID 32760673, 2020). "SKCM-TP, LUAD, HNSC, and LUSC are ranked as the top 4 cancers for potential responsiveness to anti-CTLA-4 therapy." (PMID 31991588, 2020). "Immunotherapy with checkpoint inhibitors (CPI) targeting PD-1 or CTLA-4 has emerged as an important treatment modality for several cancer forms." (PMID 32620163, 2020). "Since then, immune checkpoints inhibitors have been considered as novel targets for cancer immunotherapy, and several antibodies targeting CTLA4, PD-1, and PD-L1 are currently approved for use in a variety of different cancers." (PMID 32235561, 2020). "Ipilimumab, a CTLA-4 blocker, became the first approved immune checkpoint blocking anti-cancer drug in 2011 in the United States." (PMID 32117298, 2020). "Despite the success of anti-CTLA-4 and anti-PD-1/PD-L1 therapies, current ITs are only effective in a subset of patients, likely due to the molecular heterogeneity of cancer types." (PMID 33282963, 2020). "Immunotherapy checkpoint inhibitors, such as antibodies targeting PD-1 and CTLA-4, have demonstrated the potential of harnessing the immune system to treat cancer." (PMID 32970735, 2020). "The IS score is known to be a transcriptional predictor of anti-CTLA-4 immune checkpoint inhibitor and was assessed in the genomic data from ~10,000 human tissues across 30 different cancer types to estimate the potential response to immunotherapy." (PMID 32107458, 2020). "Human cancer therapy approaches are rapidly changing due to the successes of immunotherapy using drugs such as ipilimumab (anti-CTLA4), pembrolizumab (anti-PD-1), atezolizumab (anti-PD-L1), and tisagenlecleucel (CD19 CAR-T)." (PMID 32614928, 2020). "Side effects of cancer immunotherapy using the CTLA-4 antibody (ipilimumab) are much more serious and severe than those using the PD-1 antibodies." (PMID 32492969, 2020). "In the present study, we used a comprehensive pan-cancer approach to evaluate the clinical significance of PD-1 and CTLA4 expression in a variety of cancers." (PMID 33072070, 2020).